IDH1 (isocitrate dehydrogenase (NADP(+)) 1)
Diseases named in the same sentence as IDH1 in open-access papers (continued):
Sharing a sentence is not in itself a finding about the gene and the disease.
glioma (continued). "IDH1-R132H mutations lead to both a less aggressive phenotype and radiosensitization of glioma cells." (PMID 38612910, 2024). "Bioinformatics analysis suggests that Itgb4 expression is lower in IDH1-mutant gliomas, and lower Itgb4 levels are associated with better prognosis." (PMID 38982076, 2024). "The morphological classification of gliomas has been integrated with the introduction of genetic markers, such as the IDH1 gene encoding the enzyme, isocitrate dehydrogenase type-1, co-deletion of chromosomes 1p-19q, and deletion of X chromosome." (PMID 38509672, 2024). "IDH1/2 mutations and 1p19q codeletion are two critical mutations in gliomas, often associated with favorable patient prognosis." (PMID 39595145, 2024). "These metabolic alterations implied that the effects of the IDH1 mutation on disturbing α-KG-related amino acid metabolism were more significant in glioma cells with low OGDH expression." (PMID 39872214, 2024). "Although IDH1 mutations in glioma are most commonly the IDH1-R132H variant, alternative IDH1-R132 SNVs, including R132S, R132L, R132G, and R132C have been observed in the molecular analysis of primary tumor samples." (PMID 39596840, 2024). "Although the percentage of TA-MSCs in high-grade gliomas is found to be inversely correlated with overall survival, the fractions of GA-MSCs in tissues from three GBs with a wild-type IDH1 mutation status were only 0.7, 3.7 and 9.3%." (PMID 38396962, 2024). "There was a significant difference in TBRpeak between diffuse IDHwt gliomas and IDH1/2 mutated gliomas (p < 0.001)." (PMID 37776502, 2024). "Genes with the most prevalent mutations at different age groups were presented in both IDH1_WT and IDH1_MT glioma." (PMID 38267516, 2024). "Mutations in the IDH1 gene have been shown to be an important driver in the development of acute myeloid leukemia, gliomas and certain solid tumors, which is a promising target for cancer therapy." (PMID 39512821, 2024). "Among the 56 patients with high-grade glioma, the mutation was detected in the plasma of 5 patients (8.9%) with an IDH1 p.R132H mutant tumor." (PMID 38172718, 2024). "In Grade 4 gliomas (n = 75), 61 patients (81.3%) had IDH1 mutations and 1 patient (1.3%) had an EGFR-amp." (PMID 38893240, 2024). "The results showed that a combined evaluation of DCE-MRI and DKI parameters reveals the best prediction of high-grade vs. low-grade gliomas, IDH1/2 wildtype vs. mutated gliomas, and astrocytomas/glioblastomas vs. oligodendrogliomas." (PMID 39123372, 2024). "Multiple genetic alterations in glioma tissues, such as IDH1 mutations, 1p/19q co-deletion, and MGMT promoter methylation, serve as significant indicators of prognosis and drug responsiveness." (PMID 39574472, 2024). "Significant attention has been directed toward IDH1/2 mutations because these markers play a fundamental role in the classification of gliomas according to the revised 2016 WHO CNS guidelines." (PMID 39192888, 2024). "Mutations of isocitrate dehydrogenase 1 (IDH1) are key biomarkers for glioma classification, but current methods for detection of mutated IDH1 (mIDH1) require invasive tissue sampling and cannot be used for longitudinal studies." (PMID 39203017, 2024). "We developed a murine model of proneural IDH1R132H-mutated glioma that shows elevated production of 2-hydroxyglutarate (2-HG) and increased trimethylation of lysine residue K27 on histone H3 (H3K27me3) compared to IDH1 wild-type tumors." (PMID 38334611, 2024). "IDH1 mutations resulting in the overproduction of 2-HG contribute to initiation and progression of myeloid malignancies and gliomas." (PMID 39766049, 2024).
glioma (continued). "Taken together, PTBP1 expression is influenced by IDH1 mutations and the degree of tumour malignancy, and is associated with poor prognosis in gliomas." (PMID 38918441, 2024). "This study showed that the SVM single sequence model and combined model based on DWI, DCE, and APTW had good diagnostic performance in predicting the expression of Ki-67 and IDH-1 mutation in glioma." (PMID 39285364, 2024). "Significant differences between IDH1/2 wild \type and IDH1/2 mutated gliomas were detectable for many DCE-MRI and DWI/DKI parameters." (PMID 39123372, 2024). "Within the process of gliomagenesis, IDH1/2 mutations have been identified as frequently occurring in the early stages of human glioma development." (PMID 39457600, 2024). "In gliomas, IDH1 R132H is the most common mutation and the mutation is associated with slower progression and better prognosis." (PMID 39208202, 2024). "The investigation of genetic signatures linked to IDH1 mutations provides valuable perspectives on their significance in glioma biology." (PMID 39529768, 2024). "IDH1 gene mutation is more frequently seen in gliomas and is typically characterized by a specific mutation (R132H) that leads to a single amino acid change in the enzyme's active site." (PMID 38167551, 2024). "Gliomas with IDH1 mutations can be sub-classified into two types: those with 1p/19q co-deletion, known as ODs, and those with intact 1p/19q, identified as astrocytomas, leading to better OS in patients with OD." (PMID 38932755, 2024). "We found room for performance improvement for subgroups with lower incidence (e.g., 1p/19q codeleted or IDH1/2 mutated gliomas) and patients with rare diagnoses (e.g., pediatric gliomas, midline gliomas)." (PMID 38791871, 2024). "Isocitrate dehydrogenase-1 (IDH1) oncogene mutations were detected in gliomas, acute myeloid leukemia, some benign and malignant cartilaginous tumors, and only 1% of PCa." (PMID 39630373, 2024). "D-2HG accumulates in certain brain tumors, such as gliomas and glioblastomas, with gain-of-function mutations in the IDH1 and IDH2 genes encoding the IDH1 and IDH2 enzymes, respectively." (PMID 39201738, 2024). "Some IDH1 mutations in glioma are proposed as prognostic markers, with patients bearing mutated tumors showing improved survival." (PMID 38539663, 2024). "Patients with residual or recurrent grade 2 glioma characterized by an IDH1 or IDH2 mutation were randomly assigned to receive Vorasidenib or a placebo." (PMID 39123479, 2024). "A systematic review confirmed that adjuvant therapy with PCV was associated with improved OS and PFS versus TMZ in low-grade glioma but noted that the benefit was driven by patients with 1p/19q-codeleted tumors and IDH1 mutations." (PMID 38571509, 2024). "Mutations in IDH1/2 have been found to have a significant impact on various types of human malignancies, including gliomas, acute myeloid leukemia, cholangiocarcinoma, ovarian cancer, and chondrosarcoma." (PMID 39201639, 2024). "When comparing TBRpeak between diffuse IDHwt and IDH1/2 mutated gliomas, we found that IDHwt gliomas had a significantly higher uptake compared to IDH1/2 mutated gliomas." (PMID 37776502, 2024). "A recent genomewide mutational analysis of gliomas uncovered somatic mutations in the isocitrate dehydrogenase 1 (IDH1) gene in a subset of these tumors." (PMID 38529286, 2024).
glioma (continued). "For glioma molecular classification and prognostication, various molecular abnormalities have received considerable attention, including IDH1/2 mutations, ATRX mutations, 1p/19q co‐deletion, TERT promoter mutations, and MGMT promoter methylation." (PMID 38332637, 2024). "Genetically, the presence of IDH1/2-mutations defines a distinct class of diffuse adult glioma with overall improved prognosis as IDH-wt glioma." (PMID 39593128, 2024). "Reproducibility studies were performed using two FFPE glioma samples, cases 8 and 22, with IDH1 p.R132H and IDH2 p.R172K mutations respectively, by testing FFPE sections on three separate days." (PMID 38796421, 2024). "Accordingly, several studies highlighted the positive correlation between IDH1 p.R132H mutation and survival of patients with gliomas." (PMID 38172718, 2024). "This is in accordance with previous studies, which reported that IDH1 mutation occurs in the majority of low-grade gliomas and less frequently in high-grade gliomas." (PMID 38172718, 2024). "As such, therapies that target IDH1 mutations and downstream metabolic products, beyond having direct effects on delaying progression-free survival in low-grade gliomas, need to be considered in the context of immunomodulatory strategies." (PMID 38193532, 2024). "IDH1/2 mutations, often seen in acute myeloid leukemia, cholangiocarcinoma, and gliomas, produce an oncometabolite that disrupts DNA methylation and differentiation." (PMID 39199633, 2024). "The improvement seen in lower-grade glioma is almost certainly due to identifying IDH1 mutations via a mapping of local sequence context of that specific hotspot." (PMID 37919367, 2024). "In the Glioma/Glioblastoma cancer, 67% (16/24) of tumors exhibited one disease-related variant, of which 94% (15/16) were in IDH1 and 6% (1/16) were in PIK3CA." (PMID 38448823, 2024). "Recent advancements in the fields of radiomics, radiogenomics, and machine learning have prompted numerous studies exploring multiple directions for the prediction of IDH1 mutation status in gliomas through non-invasive methods." (PMID 39375809, 2024). "F3T3 gliomas typically lack IDH1/2 mutations and 1p/19q codeletion, which is important for their differential diagnosis towards oligodendrogliomas." (PMID 38730596, 2024). "The results of these analyses substantiate and support recent efforts to increase the extent of resection in gliomas particularly for those tumours with IDH1 mutation and for considering sex-specific associations." (PMID 39767640, 2024). "IDH1 mutations, producing the oncometabolite 2-HG that disrupts cell differentiation and influences tumor behavior, are commonly found in lower-grade gliomas and certain glioblastomas, reflecting their distinct metabolic profile." (PMID 38921472, 2024). "Our research has revealed a significant positive correlation between TBC1D1 and IDH1 mutations in glioma patients, emphasizing the crucial involvement of TBC1D1 in modulating these mutations." (PMID 38529286, 2024). "Here, in this study, samples from CNS-GBM and CNS-Oligo were combined to obtain a greater number of IDH1 mutants from both gliomas that have been relatively well studied for the IDH1 mutation-associated oncometabolites." (PMID 38468344, 2024). "For example, the classical subtype is associated with EGFR amplification, while proneural gliomas are usually linked to mutations in the IDH1 and PDGFRA genes." (PMID 39531784, 2024). "Previous work has shown that patients with grade II–IV gliomas harbouring IDH1 or IDH2 mutation had significantly longer overall survival than those without IDH mutation." (PMID 39767640, 2024).
glioma (continued). "Two trials were mutation-specific; one focused on IDH1-R132H Grade 2 glioma, while the other mutation-specific trial included tumors that had a BRAF-V600E mutation (NCT02034110)." (PMID 39337916, 2024). "To this end, we aimed to develop and validate radiomics models based on DWI, DCE, and APTW sequences to evaluate Ki-67 expression and IDH-1 mutation in gliomas." (PMID 39285364, 2024). "Both IDH mutant mouse models and human glioma patients exhibit similar genetic alterations, including the hallmark IDH1 or IDH2 mutations." (PMID 38539537, 2024). "The rat gliomas appear to share some genetic alterations with IDH1 wildtype human gliomas and rat cardiac schwannomas also harbor mutations in some of the queried cancer genes." (PMID 38232086, 2024). "Point mutations in isocitrate dehydrogenase 1 and 2 (IDH1/IDH2) genes identified in diffuse gliomas with different degrees of malignancy have become the main factor for molecular-based classification of gliomas." (PMID 39684714, 2024). "Introduction of the IDH1 R132H mutation into glioma cells resulted in a significant reduction in the migratory ability on collagen IV, an important component of the brain ECM." (PMID 39596246, 2024). "While mutation of both IDH1 and IDH2 isoforms are observed in a range of cancers, IDH1 R132H represents the main mutation (90%) in sporadic IDH mutant gliomas and is associated with more favorable outcomes." (PMID 39335096, 2024). "A lot of modern research is devoted to studying the impact of this mutation, as well as the search for therapy against IDH1-mutant types of gliomas." (PMID 39768176, 2024). "Genes with synergistic relationship with IDH1 mutations in glioma such as ATRX have been previously reported, representing a glioma subgroup distinct from those with co-mutations of IDH1 with CIC and FUBP1 mutations." (PMID 39160568, 2024). "IDH1 mutations are associated with other genetic alterations involved in glioma pathogenesis and progression." (PMID 39529768, 2024). "Somatic variants in PTEN gene were also prevalent in patients with glioma (15.0%), as well as variants in IDH1 (27.0%)." (PMID 39277826, 2024). "All four probes were characterized by cellular uptake studies with U87 glioma cells harboring a heterozygous IDH1 mutation (U87-mIDH) and the corresponding wildtype cells (U87-WT)." (PMID 39203017, 2024). "The most common IDH1 mutation found in gliomas is the Arg132 mutation, resulting in the production of a tumor-specific neoantigen called IDH1(R132H)." (PMID 38763973, 2024). "The findings on miRNA-16-1 expression are rather inconclusive:its level is reduced in gliomas with the mutated IDH1phenotype compared to wild-type IDH1 tissues;meanwhile, reduced expression of this miRNA contributes to tumor proliferation." (PMID 39539523, 2024). "Considering the significance of the IDH mutation, targeting mutant IDH1/2 shows great promise as a treatment approach for gliomas." (PMID 38932383, 2024). "The remaining genes Erbb2, Kras and Tert, and Braf and Idh1, contained variants in five and two gliomas, respectively." (PMID 38232086, 2024). "Survival analysis showed that in the whole cohort of glioma patients, low tumor grade and IDH1/2 mutation were independent factors of better prognosis." (PMID 39684714, 2024). "The results of these studies suggest that the main reason for PTBP1 as a prognostic risk factor is that PTBP1 can indicate glioma progression and IDH1 mutation status." (PMID 38918441, 2024). "An IDH1-R132H point mutated enzyme (mutation in IDH1 at R132) is seen in 80–90% of grade II-III gliomas." (PMID 39767640, 2024). "Crucially, the IDH1 mutation has a more pronounced effect on disturbing α-KG homeostasis in glioma cells with low OGDH expression." (PMID 39872214, 2024).
glioma (continued). "This study found a higher incidence of IDH1/IDH2 mutations in insular gliomas, associated with smaller tumor size at onset and lower malignancy." (PMID 39766037, 2024). "Mutations in IDH1 result in the elevated synthesis of R-2-hydroxyglutarate (R-2-HG), a metabolite implicated in the oncogenesis and progression of gliomas." (PMID 39459454, 2024). "SVM models based on DWI, DCE and APTW were highly significant for evaluating the expression of Ki-67 and IDH-1 mutation status in glioma." (PMID 39285364, 2024). "They reported a balanced accuracy of 85.6% for 2-class glioma IDH1 mutation prediction, 56.2% at 5-class glioma subtyping, 88.3% at 12-class brain tumor cancer classification, and 67.5% at a 30-class brain tumor subtyping task." (PMID 38893099, 2024). "Apparently, the existing differences in the effect of the IDH1 R132H mutation on the migratory activity of glioma cells are due to the mechanism of mutation occurrence and the cell microenvironment." (PMID 39596246, 2024). "Unlike amino acid radiotracers, high 11C-acetate uptake was associated with high-grade IDH1-wt tumors, thus facilitating differentiation from high-grade IDH1-mt and low-grade gliomas." (PMID 38932755, 2024). "We showed feasibility of the approach and discuss the implications of the results for tumor microenvironment analysis beyond IDH1 mutated glioma, specifically for potential applications in IDH wildtype glioblastoma." (PMID 38263411, 2024). "Approximately half of the gliomas were positive for the IDH1 mutation, with a slight male predominance." (PMID 38444421, 2024). "IDH1 mutations drive a glioma hypermethylator phenotype, and now define distinct subtypes of pediatric and adult glioma." (PMID 39766049, 2024). "Among the Grade 2 gliomas (n = 26), 17 cases (65.3%) exhibited IDH1 mutations, while 3 patients (11.5%) had EGFR-amp." (PMID 38893240, 2024). "For instance, IDH1 mutation has been shown to reduce leukocyte chemotaxis into gliomas in a syngenic mouse model by repressing the expression of key chemoattractant cytokine genes, including Cxcl-2, Ccl-2 and C5." (PMID 37296846, 2023). "The median overall survival in all 16 patients with IDH1 wild-type high-grade gliomas that harbored actionable mutations and received genotype-matched targeted therapies, was 14.72 months with a median progression-free survival of 7.37 months." (PMID 38143440, 2023). "In conclusion, we provide compelling evidence that IDH1 mutation is related to the efficacy of radiotherapy in WHO grade 4 glioma patients." (PMID 37952042, 2023). "A possible mechanism for this effect is the role FTO has in the context of the frequent IDH1/2 mutations in gliomas." (PMID 37444417, 2023). "Several studies have confirmed that glioma cells with IDH1 mutations display increased sensitivity to radiation in vitro." (PMID 37952042, 2023). "We also find that point mutations in IDH1/2—which are common events in adult gliomas and myeloid leukemias—also disrupt the formation of PML bodies." (PMID 38066546, 2023). "Ideally, research should have a narrow focus on more specific glioma types with a regard to their genetic and epigenetic characteristics, such as IDH1/2 gene mutations and MGMT methylation status." (PMID 37239035, 2023).